DDX21 (DExD-box helicase 21)
Description:
RNA helicase that acts as a sensor of the transcriptional status of both RNA polymerase (Pol) I and II: promotes ribosomal RNA (rRNA) processing and transcription from polymerase II (Pol II). Binds various RNAs, such as rRNAs, snoRNAs, 7SK and, at lower extent, mRNAs. In the nucleolus, localizes to rDNA locus, where it directly binds rRNAs and snoRNAs, and promotes rRNA transcription, processing and modification. Required for rRNA 2'-O-methylation, possibly by promoting the recruitment of late-acting snoRNAs SNORD56 and SNORD58 with pre-ribosomal complexes. In the nucleoplasm, binds 7SK RNA and is recruited to the promoters of Pol II-transcribed genes: acts by facilitating the release of P-TEFb from inhibitory 7SK snRNP in a manner that is dependent on its helicase activity, thereby promoting transcription of its target genes. Functions as a cofactor for JUN-activated transcription: required for phosphorylation of JUN at 'Ser-77'. Can unwind double-stranded RNA (helicase) and can fold or introduce a secondary structure to a single-stranded RNA (foldase). Together with SIRT7, required to prevent R-loop-associated DNA damage and transcription-associated genomic instability: deacetylation by SIRT7 activates the helicase activity, thereby overcoming R-loop-mediated stalling of RNA polymerases. Involved in rRNA processing. May bind to specific miRNA hairpins. Component of a multi-helicase-TICAM1 complex that acts as a cytoplasmic sensor of viral double-stranded RNA (dsRNA) and plays a role in the activation of a cascade of antiviral responses including the induction of pro-inflammatory cytokines via the adapter molecule TICAM1 (By similarity).
Synonyms: RH-II/GU; GURDB; Gu-alpha; GUA; II/Gu; RH; RH II/Gu; RH-II/GuA
Tractability: Small molecule: a structure with a bound ligand is known. PROTAC: UniProt records ubiquitination sites on it; ubiquitination databases record sites on it; its protein half-life has been measured.
Target class: Enzyme; Hydrolase
Gene: Protein-coding gene on chromosome 10 (68,956,135 to 68,985,072, forward strand). Ensembl gene ENSG00000165732.
Subcellular location: Nucleus, nucleolus; Nucleus, nucleoplasm; Cytoplasm, cytosol; Mitochondrion
Subcellular location (Human Protein Atlas): Mitotic chromosome; Nucleoli rim; Nucleoplasm
Pathways (Reactome):
Gene expression (Transcription): B-WICH complex positively regulates rRNA expression
Metabolism of RNA: Major pathway of rRNA processing in the nucleolus and cytosol
Gene Ontology:
Molecular function: 7SK snRNA binding; ATP hydrolysis activity; miRNA binding; protein binding; RNA binding; RNA helicase activity; rRNA binding; snoRNA binding; RNA polymerase inhibitor activity; ATP binding; double-stranded RNA binding; helicase activity; identical protein binding; nucleic acid binding
Biological process: osteoblast differentiation; positive regulation of transcription by RNA polymerase III; R-loop processing; transcription by RNA polymerase II; chromatin remodeling; negative regulation of transcription by RNA polymerase I; positive regulation of canonical NF-kappaB signal transduction; positive regulation of transcription by RNA polymerase I; positive regulation of transcription by RNA polymerase II; positive regulation of myeloid dendritic cell cytokine production; regulation of gene expression
Cellular component: B-WICH complex; chromosome; membrane; nucleolus; nucleoplasm; cytosol; mitochondrion
Genetic constraint (gnomAD): Loss-of-function variants: 17 observed, 87.81 expected, observed/expected ratio (o/e) 0.19, 90% interval 0.13 to 0.29. The upper end of that interval is the gene's LOEUF score, 0.29, which puts it in group 1 of 6, group 1 being the genes least tolerant of losing a copy. Missense variants: 644 observed, 950.41 expected, observed/expected ratio (o/e) 0.68, 90% interval 0.63 to 0.72. Synonymous variants: 284 observed, 324.25 expected, observed/expected ratio (o/e) 0.88, 90% interval 0.79 to 0.97.
Homologues: Orthologues: chimpanzee DDX21 (99% identical), macaque KIFBP (98% identical), dog DDX21 (90% identical), pig DDX21 (88% identical), rabbit DDX21 (88% identical), guinea pig DDX21 (86% identical), rat Ddx21 (85% identical), mouse Ddx21 (84% identical), zebrafish ddx21 (58% identical). Paralogues in human: DDX50 (57% identical), DDX18 (21% identical), DDX27 (21% identical), DDX3X (21% identical), DDX3Y (21% identical), DDX43 (20% identical), DDX17 (20% identical), DDX42 (20% identical), DDX5 (20% identical), DDX31 (20% identical), DDX46 (20% identical), DDX54 (20% identical), and 26 more.
Diseases named in the same sentence as DDX21 in open-access papers:
DDX21 is named in the same sentence as 63 diseases in open-access papers, as found by Europe PMC text mining. Sharing a sentence is not in itself a finding about the gene and the disease. The quoted sentences say what the papers report.
breast carcinoma (25 papers, 2013 to 2026). "In breast cancer, DDX21 gene expression levels have been reported to be associated with longer overall and disease-free survival." (PMID 33328538, 2020). "In contrast high levels of DDX21 expression were shown to be associated with low survival and rapid relapse in breast cancer." (PMID 23741337, 2013). "For example, although DDX21 is highly expressed in breast cancer, colorectal cancer, gastric cancer and neuroblastoma, low DDX21 levels are associated with poor clinical outcome of breast cancer patients." (PMID 36761420, 2022). "Our study reveals a novel mechanism of HIF regulation and positions DDX21 as a potential therapeutic target for disrupting the hypoxic adaptation machinery in breast cancer." (PMID 42311859, 2026). "Emerging evidence authenticated that ADP-ribosylated DDX21 caused by snoRNA-activated PARP-1 accelerated rDNA transcription, ribosome biogenesis, and protein translation, leading to the increased growth of breast cancer cells." (PMID 39866844, 2025). "Its expression correlates with cell proliferation rendering DDX21 as a potential therapeutic target in breast cancer." (PMID 40362385, 2025). "For example, miR-218-5p directly bound to the 3′-UTR of DDX21 mRNA, leading to downregulation of DDX21 in breast cancer." (PMID 39866844, 2025). "This section reviews the roles of DDX21 in cancer development, focusing on its involvement in breast cancer, colorectal cancer, gastric cancer, hematologic malignancies, and neurological disorders." (PMID 39769343, 2024). "In breast cancer, DDX21 has been identified as a marker for a subset of patients with high proliferative potential and as a potential therapeutic target." (PMID 39769343, 2024). "The phosphorylation of c-Jun at Ser73 is essential for DDX21 to promote AP-1 activity and enhance rRNA processing in multiple breast cancer cell lines." (PMID 39769343, 2024). "UTP6 was enriched in the process of snoRNA binding, while snoRNA activated PARP-1 ADPRylates DDX21 in BRCA1/2-wild-type breast cancer cells to promote enhanced ribosome biogenesis and cell proliferation." (PMID 39095659, 2024). "We previously discovered one such mechanism in breast cancer involving DDX21, an RNA helicase that localizes to the nucleoli of cells and is a target of PARP1." (PMID 38767454, 2024). "DDX21 also resolves R-loops formed during transcription, preventing RNA polymerase stalling and ensuring genome stability in breast cancer cells." (PMID 39769343, 2024). "Conversely, in human breast cancer cell lines, DDX21 also participates in transcriptional repression at the SNAIL promoter by recruiting SUZ12 from the PRC2 complex to induce histone H3K27 trimethylation (H3K27me3), suppressing SNAIL expression." (PMID 39769343, 2024). "Research on DDX21 in breast cancer has primarily focused on its role in ribosome biogenesis and transcriptional regulation." (PMID 39769343, 2024). "Our results are consistent with previous reports that DDX21 is upregulated at gene and protein levels in colorectal cancer, breast cancer, and lymphoma." (PMID 36505822, 2022). "The CPTAC data showed higher DDX21 protein levels in primary breast cancer, ovarian cancer, colon cancer, clear cell RCC, UCEC, and LUAD tissues (p < 0.001) than in normal tissues." (PMID 36505822, 2022). "DDX21 is overexpressed in human breast and colon cancer tissues and contributes to leukemogenesis and breast cancer tumorigenesis." (PMID 33497018, 2021). "By resolving estrogen‐induced R loops on estrogen‐responsive genes in breast cancer cells, DDX21 promotes transcription elongation." (PMID 33497018, 2021). "The activation of PARP by snoRNAs ADPRylates the RNA helicase DDX21, which, in turn, stimulates rRNA production, ribosome levels, and translation in breast cancer cells." (PMID 33946178, 2021).
breast carcinoma (continued). "Upregulation of DDX21 promotes breast cancer cell proliferation by activation of the transcription factor AP-1 to regulate the transcription of cyclin D1 and rRNA processing, resulting in the increase of cells in the S phase." (PMID 34207140, 2021). "Inhibition of PARP decreases the activity of DDX21 and suppresses cell proliferation in breast cancer cells." (PMID 34207140, 2021). "Another study revealed that significant overexpression DDX21 promoted breast cancer proliferation and development by interacting with c-Jun to activate AP-1 activity, suggesting a critical role of DDX21 in tumorigenesis and development." (PMID 33202381, 2020). "Recent work has highlighted that DDX21 unwinds R-loop, thus safeguarding genome integrity and prevent stalling of RNA Pol II on estrogen-responsive genes in breast cancer cells." (PMID 31251802, 2019). "DDX21 is highly expressed in breast carcinomas; it can promote tumorigenesis by enhancing RNA processing in breast cancer cells." (PMID 29472942, 2018). "DDX21 was found to localize to the nucleus and nucleolus in a number of breast cancer tissues as well as in numerous established breast cancer cell lines." (PMID 25260534, 2014). "DDX21 mRNA expression has been correlated with disease-free survival in breast cancer patients and accumulation of DDX21 has been observed in colon cancers and lymphomas." (PMID 25260534, 2014). "Taken together, these results show that elevated DDX21 expression is required in order to maintain the viability and cell cycle progression of highly proliferative breast cancer cells." (PMID 25260534, 2014). "To assess the long-term effects of DDX21 deficiency on proliferation and tumorigenesis, we utilized multiple shRNAs targeting endogenous human DDX21 to effectively knock down DDX21 protein expression in three highly proliferative breast cancer cell lines." (PMID 25260534, 2014). "Surprisingly, a significant number of breast cancer tissues and breast cancer cell lines show nuclear localization of DDX21 protein." (PMID 25260534, 2014). "Taken together, DDX21 is highly expressed in a significant portion of breast cancer tissues where it localizes to either nuclei or nucleoli." (PMID 25260534, 2014). "We next performed immunofluorescence analysis to determine the cellular localization of endogenous DDX21 in the same panel of established breast cancer cell lines." (PMID 25260534, 2014). "Nearly 20% of breast tumor tissues exhibited stronger immunostaining of DDX21 than the paired normal breast tissue in grade I to grade III breast carcinomas." (PMID 25260534, 2014). "Apart from its predominant nucleolar localization in many breast cancer cells, we also found that DDX21 localized to the nucleoplasm in a significant number of breast cancer tissues as well as established cancer cell lines." (PMID 25260534, 2014). "In multiple breast cancer cell lines, DDX21 protein knockdown triggered cell cycle arrest as well as massive cell death and caused a significant reduction in anchorage-independent cell growth in vitro as well as in vivo." (PMID 25260534, 2014). "DDX21 expression is high in many primary human breast tumors (and herein) and established breast cancer cell lines." (PMID 25260534, 2014). "Knockdown of DDX21 resulted in dramatic increases in cell death in numerous breast cancer cell lines." (PMID 25260534, 2014). "DDX21 expression was required to maintain breast cancer survival and proliferation in an in vivo mouse mammary gland." (PMID 25260534, 2014). "We report here that DDX21 is overexpressed in a significant number of human breast cancers (up to 25%)." (PMID 25260534, 2014). "First, we performed immunofluorescence staining for DDX21 with a breast tumor tissue array including 67 cases of various stages and subtypes of human breast cancer." (PMID 25260534, 2014).
breast carcinoma (continued). "Our findings indicate that DDX21 expression in breast cancer cells can promote AP-1 activity and rRNA processing, and thus, promote tumorigenesis by two independent mechanisms." (PMID 25260534, 2014). "Importantly, DDX21 is highly expressed in breast tumors and correlates negatively with clinical outcomes in breast cancer patients." (PMID 42311859, 2026). "Consequently, DDX21 enhances breast cancer cell proliferation, survival, migration, and invasion in vitro, and promotes breast tumor growth and metastasis in vivo." (PMID 42311859, 2026). "Moreover, DDX21 was highly expressed in breast cancer tissues and contributed to tumorigenesis via activation of c-Jun activity and rRNA processing." (PMID 39866844, 2025). "Furthermore, Ddx21 has been identified as a prognostic indicator in breast cancer through gene expression profiling." (PMID 38993792, 2024). "Consistently, DDX21 could stimulate breast cancer cell proliferation through activation of PARP-1, rDNA transcription, ribosome biogenesis, and protein translation." (PMID 37072811, 2023). "In contrast, DDX21 was found to act on Snail gene promoter and epigenetically repressed its transcription resulting in suppression of epithelial-mesenchymal transition and invasion of breast cancer cells." (PMID 35371306, 2022). "In addition, DDX21 is highly expressed in human breast cancer tissues and DDX21 protein expression level correlates with cancer cell proliferation rate, while mechanistically, DDX21 induces AP‐1 transcriptional activity and c‐Jun protein phosphorylation." (PMID 33497018, 2021). "DDX21 is dysregulated in colon cancer, lymphomas, neuroblastoma, and some breast cancers." (PMID 34207140, 2021). "Contrary to our results, a study of breast cancer displayed that DDX21 low expression was correlated with higher metastasis and poor clinical prognosis, and knockdown of DDX21 promoted breast cancer cells epithelial-mesenchymal transition (EMT), invasion and migration in vitro and in vivo." (PMID 33202381, 2020). "Furthermore, analyses of gene expression profiles from breast cancer patients identified DDX21 as a prognostic marker in breast cancer." (PMID 32640701, 2020). "DDX21 promotes c-Jun activity by EGF signaling in the tumorigenesis of breast cancer." (PMID 27835882, 2016). "Additionally, The Cancer Genome Atlas (TCGA) datasets from recently sequenced human basal breast cancer samples showed overexpression of DDX21 mRNA in 14/81 (17%) samples (cBioPortal)." (PMID 25260534, 2014). "Given the elevated protein expression of DDX21 in highly proliferative breast cancer cell lines, we sought to determine whether DDX21 was an essential protein for cell proliferation and survival." (PMID 25260534, 2014). "In this study, we found DDX21 overexpressed in highly proliferative primary breast carcinomas." (PMID 25260534, 2014). "Herein, we show that DDX21 is highly expressed in breast cancer tissues and established cell lines." (PMID 25260534, 2014). "DDX21 is highly expressed in colon cancer, lymphomas, and some breast cancers, but little is known about how DDX21 might promote tumorigenesis." (PMID 25260534, 2014). "To determine whether DDX21 is a critical component of rRNA processing in our breast cancer system where DDX21 is primarily nucleolar, we first performed an rRNA pulse-chase assay with HCC1806 cells in which DDX21 localizes to the nucleolus." (PMID 25260534, 2014). "We performed immunohistochemistry staining for DDX21 with several sets of human breast cancer tissue samples to determine whether DDX21 overexpression occurs in breast cancer." (PMID 25260534, 2014). "We first examined whether DDX21 interacted with c-Jun in our panel of established breast cancer cell lines." (PMID 25260534, 2014). "DDX21 could serve as a marker for a subset of breast cancer patients with higher proliferation potential and may be used as a therapeutic target for a subset of breast cancer patients." (PMID 25260534, 2014).
breast carcinoma (continued). "Similarly, immunostaining of a third breast cancer tissue array showed that DDX21 was highly expressed in 16 out of 70 cases." (PMID 25260534, 2014). "We also analyzed DDX21 protein levels in a panel of established breast cancer cell lines." (PMID 25260534, 2014). "As c-Jun is a critical component of the AP-1 transcription factor, we hypothesized that DDX21 might somehow modulate AP-1 activity in breast cancer cells." (PMID 25260534, 2014). "Our results demonstrate that DDX21 is an important growth and proliferation modifier that regulates oncogene-induced mammary tumorigenesis, and implicate its potential therapeutic value in breast cancers." (PMID 25260534, 2014). "Additionally, DDX21 promotes rRNA processing in multiple breast cancer cell lines." (PMID 25260534, 2014). "In BRCA1/2-wild-type breast cancer cells, snoRNA activates PARP-1, leading to ADP-ribosylation of Ddx21, thereby enhancing ribosome biogenesis and cell proliferation." (PMID 38993792, 2024). "The top predicted pan-cancer regulators including RSL1D1, DDX21 and SMC2, were experimentally validated in lung, colon, breast cancer and fetal kidney cells." (PMID 38102665, 2023). "In breast cancer, H/ACA snoRNAs are also able to regulate the activity of DDX21 by interacting with the PARP enzyme, which catalyzes the addition of poly(ADP-ribose) (PAR) polymers on target proteins." (PMID 33946178, 2021). "However, some studies indicate that DDX5, DDX21, and DDX3X exert tumor suppressor function in different cancers, such as hepatocellular carcinoma (HCC), breast cancer (BC) and colorectal cancer (CRC)." (PMID 35723050, 2022). "Nevertheless, research into the role of DDX21 in tumors has largely been restricted to specificcancer types, such as breast cancer and ACC (adrenocortical carcinoma), and no pan-cancer analysis of the link between DDX21 and other cancers has been performed." (PMID 36505822, 2022). "A significant number of mammary tumor tissues and established breast cancer cell lines exhibit nuclear but not nucleolar localization of DDX21." (PMID 25260534, 2014). "In this report, we found that DDX21 is highly expressed in breast cancer tissues compared to normal breast tissue and its expression is pivotal to maintain enhanced breast cancer cell proliferation and growth." (PMID 25260534, 2014). "However, not all of Ki67-positive breast cancer tissues displayed strong DDX21 staining, suggesting that DDX21 is not simply a marker of proliferation." (PMID 25260534, 2014). "Additionally, DDX21 interacts with EZH2 and SUZ12 at the SNAIL promoter to enhance H3K27me3, epigenetically repressing SNAIL transcription and thereby inhibiting epithelial–mesenchymal transition (EMT) and suppressing breast cancer cell invasion and metastasis." (PMID 39769343, 2024).